RNU6-90P (RNA, U6 small nuclear 90, pseudogene)
Gene: Small nuclear RNA gene on chromosome 15 (51,907,200 to 51,907,305, forward strand). Ensembl gene ENSG00000272337.
Homologues: Orthologues: chimpanzee U6 (100% identical), macaque U6 (95% identical), pig U6 (81% identical), guinea pig U6 (70% identical). Paralogues in human: RNU6-1181P (90% identical), RNU6-106P (88% identical), RNU6-1241P (88% identical), RNU6-1145P (87% identical), RNU6-1201P (87% identical), RNU6-12P (87% identical), RNU6-1316P (87% identical), RNU6-13P (87% identical), RNU6-16P (87% identical), RNU6-188P (87% identical), RNU6-32P (87% identical), RNU6-393P (87% identical), and 1285 more.